RNU6-1081P (RNA, U6 small nuclear 1081, pseudogene)
Gene: Small nuclear RNA gene on chromosome 2 (11,233,988 to 11,234,094, forward strand). Ensembl gene ENSG00000207267.
Homologues: Orthologues: chimpanzee U6 (98% identical), pig U6 (88% identical), macaque U6 (86% identical). Paralogues in human: RNU6-15P (90% identical), RNU6-10P (89% identical), RNU6-1145P (89% identical), RNU6-1316P (89% identical), RNU6-20P (89% identical), RNU6-211P (89% identical), RNU6-25P (89% identical), RNU6-310P (89% identical), RNU6-35P (89% identical), RNU6-41P (89% identical), RNU6-46P (89% identical), RNU6-1 (88% identical), and 1289 more.